FGF18 (fibroblast growth factor 18)
Description:
Plays an important role in the regulation of cell proliferation, cell differentiation and cell migration. Required for normal ossification and bone development. Stimulates hepatic and intestinal proliferation.
Synonyms: FGF-18; ZFGF5
Tractability: Small molecule: it belongs to a druggable protein family. Antibody: its Gene Ontology location is reachable by antibodies, with high confidence; UniProt places it where antibodies can reach, with medium confidence; UniProt predicts a signal peptide or a membrane-spanning region.
Gene: Protein-coding gene on chromosome 5 (171,419,645 to 171,457,626, forward strand). Ensembl gene ENSG00000156427.
Subcellular location: Secreted
Pathways (Reactome):
Signal Transduction: FGFR2c ligand binding and activation; FGFR3b ligand binding and activation; FGFR3c ligand binding and activation; FGFR4 ligand binding and activation; FGFRL1 modulation of FGFR1 signaling; FRS-mediated FGFR2 signaling; FRS-mediated FGFR3 signaling; FRS-mediated FGFR4 signaling; Negative regulation of FGFR2 signaling; Negative regulation of FGFR3 signaling; Negative regulation of FGFR4 signaling; PI-3K cascade:FGFR2; PI-3K cascade:FGFR3; PI-3K cascade:FGFR4; PI3K Cascade; PI5P, PP2A and IER3 Regulate PI3K/AKT Signaling; PIP3 activates AKT signaling; Phospholipase C-mediated cascade; FGFR2; Phospholipase C-mediated cascade; FGFR3; Phospholipase C-mediated cascade; FGFR4; RAF/MAP kinase cascade; SHC-mediated cascade:FGFR2; SHC-mediated cascade:FGFR3; SHC-mediated cascade:FGFR4
Disease: Activated point mutants of FGFR2; Constitutive Signaling by Aberrant PI3K in Cancer; Signaling by FGFR2 in disease; Signaling by FGFR3 in disease; Signaling by activated point mutants of FGFR3
Gene Ontology:
Molecular function: type 1 fibroblast growth factor receptor binding; type 2 fibroblast growth factor receptor binding; growth factor activity
Biological process: positive regulation of angiogenesis; positive regulation of blood vessel endothelial cell migration; positive regulation of endothelial cell chemotaxis to fibroblast growth factor; positive regulation of MAP kinase activity; regulation of endothelial cell proliferation; regulation of sprouting angiogenesis; anatomical structure morphogenesis; cell-cell signaling; fibroblast growth factor receptor signaling pathway; neurogenesis; positive regulation of cell population proliferation; positive regulation of MAPK cascade; regulation of cell migration; signal transduction
Cellular component: nucleolus; cytoplasm; extracellular region
Genetic constraint (gnomAD): Loss-of-function variants: 5 observed, 22.02 expected, observed/expected ratio (o/e) 0.23, 90% interval 0.12 to 0.48. The upper end of that interval is the gene's LOEUF score, 0.48, which puts it in group 2 of 6, group 1 being the genes least tolerant of losing a copy. Missense variants: 180 observed, 294.72 expected, observed/expected ratio (o/e) 0.61, 90% interval 0.54 to 0.69. Synonymous variants: 117 observed, 121.09 expected, observed/expected ratio (o/e) 0.97, 90% interval 0.83 to 1.13.
Homologues: Orthologues: chimpanzee FGF18 (100% identical), macaque FGF18 (100% identical), mouse Fgf18 (98% identical), pig FGF18 (98% identical), guinea pig FGF18 (95% identical), rat Fgf18 (90% identical), zebrafish fgf18a (66% identical), rabbit FGF18 (62% identical), zebrafish fgf18b (62% identical), dog FGF6A (55% identical). Paralogues in human: FGF8 (52% identical), FGF17 (49% identical), FGF13 (28% identical), FGF3 (26% identical), FGF10 (25% identical), FGF4 (25% identical), FGF14 (24% identical), FGF20 (24% identical), FGF6 (24% identical), FGF11 (23% identical), FGF9 (23% identical), FGF7 (23% identical), and 9 more.
Diseases named in the same sentence as FGF18 in open-access papers:
FGF18 is named in the same sentence as 94 diseases in open-access papers, as found by Europe PMC text mining. Sharing a sentence is not in itself a finding about the gene and the disease. The quoted sentences say what the papers report.
osteoarthritis (19 papers, 2014 to 2025). A noninflammatory degenerative joint disease occurring chiefly in older persons, characterized by degeneration of the articular cartilage, hypertrophy of bone at the margins and changes in the synovial membrane. "FGF18 is linked to osteoarthritis (OA) progression, but its relationship with FOXN2 and its roles in post-traumatic osteoarthritis (PTOA) remain unclear." (PMID 41323462, 2025). "Low levels of FGF18 are associated with osteoarthritis pathology, where FGF18-mediated PI3K/AKT signaling is critical to promote chondrocyte proliferation, suppress IL-1β-mediated chondrocyte apoptosis, reduce oxidative stress, and restore mitochondrial function." (PMID 39766329, 2024). "FGF18 has emerged as an important therapeutic target in osteoarthritis, with recombinant human FGF18 (sprifermin) showing promising results in clinical trials for primary OA." (PMID 41323462, 2025). "Our findings align with and extend the clinical evidence from trials investigating recombinant human FGF18 (sprifermin) in osteoarthritis patients." (PMID 41323462, 2025). "By utilizing chondrocyte affinity peptide (CAP)-conjugated heteroexosomes (CAP/FGF18-hyexo) loaded with FGF18-targeting gene editing tools, a CRISPR/Cas9-based approach efficiently activates the FGF18 gene in osteoarthritis chondrocytes in vivo." (PMID 38962005, 2024). "Meanwhile, sprifermin (recombinant human FGF18) has been clinically used as a disease-modifying osteoarthritis drug in phase I and Ib studies." (PMID 36871047, 2023). "FGF18 was used to treat osteoarthritis, a cartilage injury disease, though the study was terminated due to low recruitment." (PMID 36102060, 2022). "Specifically, these approaches are set on the hurdles of cartilage regeneration, with particular attention on the fibroblast growth factor 18 (FGF-18) which induces cartilage growth and reduces cartilage degeneration in osteoarthritis." (PMID 36387077, 2022). "Although both factors’ roles in cartilage development are similar, relevant studies demonstrated VEGF degradational effect; however, in contrast, FGF18 protective and regeneration stimulating effect on cartilage in osteoarthritis." (PMID 34698129, 2021). "Our data provide evidence for the FGF-signaling cascade (FGFR3, FGF18, and PIK3R1) being causally involved in osteoarthritis." (PMID 34450027, 2021). "Sprifermin, recombinant human fibroblast growth factor 18 (rhFGF18), induces cartilage regeneration in knees of patients with osteoarthritis (OA)." (PMID 32265494, 2020). "Sprifermin (recombinant human fibroblast growth factor 18) is in clinical development as a potential disease-modifying osteoarthritis drug (DMOAD)." (PMID 29233174, 2017). "This includes development of FGF21 based therapeutics for metabolic syndrome, of FGF7 for oral mucositis and of FGF18 in osteoarthritis, it is likely that we will see FGF biologics in clinical use in the West, as well as in the East." (PMID 26793421, 2016). "Based on these reports as well as the fact that injection of rhFGF18 prevented cartilage degeneration in rat osteoarthritis models, FGF18 is believed to protect articular cartilage from intra-articular injury." (PMID 25544847, 2014). "Furthermore, recombinant human FGF18 has been under development by Merk as sprifermin, a drug with the potential to act as a disease-modifying compound for the treatment of osteoarthritis." (PMID 41323462, 2025). "In addition, recent studies showed that intra-articular injection of FGF18 ameliorates oxidative stress in an osteoarthritis model, which supports the potential regulatory function of FGF18 upon oxidative stress." (PMID 36871047, 2023). "FGF18 was reported to be anti osteoarthritis by promoting PI3K-AKT signaling pathway." (PMID 37640697, 2023). "FGF‐18 in osteoarthritis is different from FGF‐8 because it mainly protects cartilage." (PMID 35001536, 2022). "FGF18 is currently being tested in clinical trials for its effectiveness in osteoarthritis." (PMID 34450027, 2021).
osteoarthritis (continued). "Indeed, the use of FGF18 to treat osteoarthritis is progressing through clinical trials." (PMID 26793421, 2016). "The expression of FGF18 in the cartilage from PTOA and NC trauma patients was explored to identify its role in osteoarthritis development or progression." (PMID 41323462, 2025). "FGF‐18, a high‐affinity ligand for FGFR3, is the only FGF‐based drug currently used in clinical trials for osteoarthritis." (PMID 35001536, 2022). "Human cartilage explants from replaced osteoarthritis knees were cultured for ten weeks in the presence of growth factors, insulin-like growth factor 1 (IGF-1) or recombinant human fibroblast growth factor 18 (rhFGF-18)." (PMID 30404167, 2018).
ovarian carcinoma (13 papers, 2014 to 2025). A malignant neoplasm originating from the surface ovarian epithelium. "Amplification of the chromosomal region 5q31-5q35.3, where FGF18 is located, is strongly associated with poor prognosis in ovarian cancer patients." (PMID 40330466, 2025). "FGF18 is also a prognostic and therapeutic biomarker for certain types of ovarian cancers, while its underlying pathophysiological role in ccRCC progression remains elusive." (PMID 33117668, 2020). "Four of these factors (FGF18, HERC5, RPS27A, and hsa-miR-202) were found to be associated with ovarian cancer in previous literatures." (PMID 38182734, 2024). "Enhancement of tumor progression by FGF18 has also been shown in ovarian cancer and hepatocellular carcinoma." (PMID 37340889, 2023). "In ovarian cancer, FGF18 was identified as a blood‐based biomarker by secretome analysis and enhanced FGF18 levels were confirmed by ELISA in the blood from ovarian cancer patients compared with a control group." (PMID 37340889, 2023). "In exploring the progression of the tumor-promoting mechanism of FGF18 in epithelial ovarian cancer." (PMID 37228502, 2023). "Four of these factors (FGF18, HERC5, hsa-miR-202, and RPS27A) were found to be associated with ovarian cancer in previous literatures." (PMID 37609286, 2023). "ovarian cancer cells, FGF18 mRNA and protein levels were increased in serous ovarian tumors relative to normal ovarian epithelium as analyzed by qRT-PCR and immunohistochemistry (IHC)." (PMID 37228502, 2023). "Previous studies have reported a prominent role of FGF18 in tumorigenesis, proliferation, and metastasis of several tumors, including gastric cancer, ovarian cancer, and breast cancer." (PMID 35277183, 2022). "We concluded that PAX8 promoted ovarian cancer cell migration, at least partially, through activating the autocrine FGF18-FGFR signaling pathway." (PMID 31050342, 2019). "FGF18 was also highly expressed in malignant tissue as well as normal ovarian tissue, suggesting that FGF19 may be more ovarian cancer–specific compared with FGF18." (PMID 38273381, 2024). "In 2013, Wei’s team predicted that overexpression of FGF18 was an independent marker for poor prognosis of ovarian cancer, and determined that FGF18 was a serum biomarker of ovarian cancer, which was significantly correlated with the prognosis and progression of ovarian cancer." (PMID 37228502, 2023). "FGF18 overexpression has been considered a potential prognostic biomarker in several types of tumors including hepatocellular cancers, colorectal cancer, and ovarian cancer." (PMID 33117668, 2020). "In summary, several markers showed substantially elevated expression levels between ovarian cancer compared with benign conditions in publically available expression data and our proof of concept study (including recently suggested marker FGF18) for ovarian cancer prediction." (PMID 31336942, 2019). "Here, we hypothesize that one way in which PAX8 confers a proliferative advantage to ovarian cancer cells is through the regulation of procancer factors, like FGF18, in a pathological microenvironment." (PMID 27259239, 2016). "Thus, FGF18 is a potential therapeutic target, and its inhibition could offer a novel treatment approach for ovarian cancer." (PMID 40330466, 2025). "ovarian cancer cells showed that FGF18 could function through the PAX8-FGF18 axis pathway." (PMID 37228502, 2023). "In addition, LOC401317 could induce apoptosis in the nasopharyngeal carcinoma cell line HNE2, and FGF18 (Fibroblast growth factor 18) is a prognostic and therapeutic biomarker for ovarian cancer." (PMID 30289891, 2018). "Of particular importance, FGF18 was specifically involved in regulating ovarian cancer cell migration without affecting tumor outgrowth, which was verifiable across different models." (PMID 31050342, 2019).
ovarian carcinoma (continued). "In addition to PAX8, COPA complemented with pan-cancer analysis prioritized eight other lineage-restricted outliers (CDH6, CLDN16, FGF18, FOLR1, SLC34A2, SOX17, SPON1, WNT7A) displaying largely confined gene expression in ovarian cancer cell lines and tumor specimens." (PMID 31050342, 2019).
breast carcinoma (11 papers, 2013 to 2025). "By Kaplan Meier analysis, defining the risk of breast cancer recurrence, FGF18 was significantly correlated with disease-free survival (DFS) of breast cancer." (PMID 37228502, 2023). "In DNA methylation spectrum epigenetic changes, predict FGF18 significantly associated with breast cancer, breast cancer is likely to be obese and important intermediate of biomarkers." (PMID 37228502, 2023). "In terms of clinical relevance of FGF18, FGF18 is a valid diagnostic marker in breast cancer." (PMID 37228502, 2023). "In summary, FGF18 helps us to have a more systematic understanding of the genetic and molecular protein aspects in the prediction and treatment of breast cancer progression." (PMID 37228502, 2023). "Analysis of FGF18 gene and protein levels by Oncomine cancer Genome Atlas database and Human Protein Atlas database showed that FGF18 expression was increased in breast cancer compared with normal tissues." (PMID 37228502, 2023). "FGF18 copy number and mRNA levels have previously been shown to be increased in breast cancer compared with normal breast tissue." (PMID 37546410, 2023). "An in vitro study showed that FGF18 was induced during hypoxia and involved in cell cycle regulation and migration of breast cancer cells." (PMID 37546410, 2023). "Stimulation of human breast cancer cell line MDA-MB-231 with FGF18 recombinant protein enhanced its proliferation ability and increased the number of colonies formed." (PMID 37228502, 2023). "FGF11 and FGF18 were also found to be associated with MBD in our cohort, however limited information exists on their role in MBD or breast cancer." (PMID 37546410, 2023). "The proliferation, migration and invasion of human breast cancer cell line MDA-MB-231 with FGF18 knockdown or overexpression were significantly affected by WB, qPCR and other technologies." (PMID 37228502, 2023). "Breast cancer-related genes were screened in the GEO database and found that FGF18 was statistically significant with the progression of breast cancer." (PMID 37228502, 2023). "Both FGF8 and FGF18 have a role in regulating the cell cycle of breast cancer cells, a finding that deserves further investigation in the search for novel potential treatments for patients with highly proliferative breast cancer." (PMID 35193394, 2022). "In breast cancer, FGF18 promotes cell proliferation through the ERK/c-Myc signaling pathway and stimulates the production of epithelial-to-mesenchymal transition (EMT) factors, thus, promoting neoplastic cell migration and invasion." (PMID 36359024, 2022). "We developed a prognostic tool for early breast cancer based on the analysis of the relative expression level of FGF18, BCL2, PRC1, MMP9 and SERF1A in combination." (PMID 23648477, 2013). "The breast cancer pathway was further activated through the FGF18, HEYL, and WNT11 genes." (PMID 37887323, 2023). "By WB, qPCR and other techniques, we found that FGF18 could enhance the proliferation, migration and invasion of human breast cancer cells MDA-MB-231 through ERK phosphorylation and c-Myc signaling pathway activation." (PMID 37228502, 2023). "In terms of exploring the progress of FGF18 in breast cancer cells." (PMID 37228502, 2023). "In exploring the mechanism of FGF18 in breast cancer progression." (PMID 37228502, 2023). "Therefore, FGF18 regulates breast cancer cell growth and tissue progression through Akt-GSK3β-mediated β-catenin signaling." (PMID 37228502, 2023). "By IHC staining, FGF18 protein levels were significantly increased in breast cancer tissues." (PMID 37228502, 2023). "In breast cancer, FGF18 has been shown to be involved in both cell migration and EMT." (PMID 36982180, 2023). "Conversely, different from human breast cancer, miR-21 had a very high likelihood of targeting to 3′ UTR of the fibroblast growth factor 18 FGF18 (score 97 in miRDB) mRNA." (PMID 36359024, 2022).
breast carcinoma (continued). "In the same human breast cancer cell lines MDA-MB-453 and SK-BR-3, the mRNA levels of some proliferation-related genes, such as CCND2, CDK2 and Ki67, were significantly up-regulated when stimulated by recombinant FGF18 protein." (PMID 37228502, 2023).
gastric cancer (8 papers, 2019 to 2025). A primary or metastatic malignant neoplasm involving the stomach. "Additionally, FGF18 downregulation inhibits gastric cancer development, causes G1-phase cell cycle arrest, and improves anticancer treatment sensitivity." (PMID 37108717, 2023). "Specifically, the activation of the tumor necrosis factor receptor-associated factor 6 (TRAF6)/NF-κB/fibroblast growth factor 18 (FGF18) pathway is required for gastric cancer cell proliferation through METTL3-mediated m6A methylation." (PMID 40986143, 2025). "These investigations identified FGF18 as a novel prognostic indicator of colon cancer development and a therapeutic target in gastric cancer." (PMID 37108717, 2023). "This study aims to comprehensively investigate the expression and functional role of FGF18 in gastric cancer (GC) and elucidate its regulatory mechanisms." (PMID 30082912, 2019). "However, the molecular network structure of FGF18 in gastric cancer still needs to be further explored." (PMID 37228502, 2023). "Human recombinant FGF18 protein and FGF18 conditioned medium were used to stimulate AGS and other gastric cancer cell lines." (PMID 37228502, 2023).
colorectal cancer (7 papers, 2010 to 2021). A primary or metastatic malignant neoplasm that affects the colon or rectum. "In colorectal cancers for instance, FGF18 is upregulated through the constitutive activation of the Wnt signaling, suggesting the role of FGF18 as a downstream target of β-catenin." (PMID 30082912, 2019). "With regard to FGF18, our observations in AEG contradict older reports: our previously published findings on FGF18 expression demonstrated increased tumor cell survival and migration caused by FGF18 expression in colorectal cancer." (PMID 31527546, 2019). "This would be in agreement with our previous data in glioblastoma, where FGF5 enhanced proliferation and tube formation of endothelial cells and related data in colorectal carcinoma, where tumor cell-secreted FGF18 increased the proliferation of endothelial cells and fibroblasts." (PMID 29152117, 2017). "Interestingly, previous studies have shown that TCF/LEF, activated downstream of WNT-β-catenin signaling in colorectal cancer cells, binds to the promoter regions of FGF18 and FGF20." (PMID 22383889, 2012). "Our data show that FGFR3-IIIc exerts oncogenic functions by mediating FGF18 effects in colorectal cancer and may constitute a promising new target for therapeutic interventions." (PMID 20234367, 2010). "Previously, our group has studied a CD44-positive stem-like population in colorectal cancer (CRC) and identified a wnt-driven FGF18-dependent autocrine-signaling loop as a strong driver of tumor cell survival." (PMID 31527546, 2019). "In summary, our data demonstrate that FGFR3-IIIc exerts oncogenic effects in colorectal cancer cells by promoting in vitro tumour cell growth, survival, migration and responsiveness to oncogenic FGF ligands such as FGF18." (PMID 20234367, 2010).